NOD2 (nucleotide binding oligomerization domain containing 2)
Diseases named in the same sentence as NOD2 in open-access papers (continued):
Sharing a sentence is not in itself a finding about the gene and the disease.
Crohn disease (continued). "Although NOD2 was strongly associated with Crohn's disease location, behaviour, and age at diagnosis, adjustment for the other phenotypes showed that the association of NOD2 with behaviour was driven almost entirely by its phenotypic correlation with location and age at diagnosis." (PMID 26490195, 2016). "In addition, the NOD2 variant rs2066844, which is associated with susceptibility to Crohn’s disease, was significantly correlated with an impairment in MBL-MASP functional activity." (PMID 27404661, 2016). "Previous studies also revealed the association between CARD15 gene polymorphisms and other human diseases; for instance, a study showed that NOD2 gene variations contribute to Crohn’s disease susceptibility by altering the recognition of microbial pathogens, which changes the activation of NF-kB." (PMID 26244859, 2015). "Moreover, for Crohn’s Disease, nod2 polymorphism had been shown as a risk factor, increasing in 15–40 fold the chance of developing disease." (PMID 25643148, 2015). "Three different non-synonomous NOD2 polymorphisms – R702W, G908R, and L1007fsincC – account for roughly 80% of all NOD2-associated cases of Crohn’s disease and are reported to result in a loss of receptor function in response to muramyl dipeptide (MDP) stimulation." (PMID 26500656, 2015). "Genetic variants in NOD2 are the strongest susceptibility factor to Crohn's disease." (PMID 26320862, 2015). "Using an overexpression system, we analyzed ~50 NOD2 polymorphisms reportedly connected to Crohn’s disease to determine if they also displayed loss of function and if this could be related to alterations in protein localization and/or association with RIPK2." (PMID 26500656, 2015). "Finally, we show that SNPs associated with Crohn’s disease preferentially affect gene expression within neutrophils, including the archetypal NOD2 locus." (PMID 25955312, 2015). "Homozygous mutations in NOD2 account for 10 – 15% of patients with Crohn’s disease (CD)." (PMID 25705128, 2015). "The importance of NOD2 in protection against inflammatory bowel disease has been highlighted by the fact that particular mutations in NOD2 are associated with susceptibility to Crohn's disease." (PMID 24521784, 2014). "The nucleotide-binding oligomerization domain containing-2 gene, commonly involved in multifactorial risk of Crohn’s disease, and interleukin 10 receptor genes, associated with rare forms of early onset inflammatory bowel diseases, were sequenced in an early onset patient." (PMID 24595243, 2014). "Interestingly, NOD2 mutations and single-nucleotide polymorphisms in Atg16L1 are well-known features of Crohn’s disease." (PMID 25009542, 2014). "In addition to susceptibility to Crohn’s disease and Blau syndrome, NOD2 polymorphisms are associated with susceptibility to mycobacterial infections." (PMID 24625812, 2014). "Although not tested here, based on our data, we suggest that HCMV colitis in patients with Crohn's disease could represent a specific outcome of virus-host interaction in a subset of patients that carry mutations in the NOD2 gene." (PMID 24671169, 2014). "However, overexpression of a mutant NOD2, 3020insC, associated with severe Crohn's disease, results in enhanced HCMV replication and decreased levels of IFN-β in U373 cells." (PMID 24671169, 2014). "Interestingly, granulomas also commonly occur in the gastrointestinal tract in Crohn’s disease, and a subset of Crohn’s patients carry polymorphisms in NOD2, which are generally believed to confer loss of function." (PMID 25136265, 2014). "In addition, polymorphisms of Nod2 have been linked with susceptibility to Crohn's disease, while polymorphisms of Rip2 have been linked with systemic lupus erythematosus." (PMID 24733360, 2014). "Besides Crohn’s disease, other disease entities seem to be related to mutations in the NOD2 gene like GvHD, acute septicemia, spontaneous bacterial peritonitis in liver cirrhosis and worsened outcome after intestinal transplantation." (PMID 24597572, 2014).
Crohn disease (continued). "Whether the Crohn's disease-associated NOD2 variants confer a gain- or loss-of-function remains controversial." (PMID 23936340, 2013). "However, TLR4 and NOD2 were significantly associated with susceptibility to Crohn's disease in children in single gene analysis and gene-gene interactions." (PMID 23691182, 2013). "Despite the prevalence of NOD2-deficient models, there remains controversy as to whether Crohn’s disease-linked mutations in NOD2 diminish or enhance its activity in the context of the disease." (PMID 24137163, 2013). "The decreased production of β-defensins in Crohn’s disease may respond to individuals carrying mutations in the nucleotide-binding oligomerization domain protein 2 gene (NOD2/CARD15) gene." (PMID 25436887, 2013). "In addition, mutations within the LRR domain of NOD2 are associated with increased susceptibility to Crohn's disease." (PMID 23936340, 2013). "Three genetic NOD2 variants are known to be strongly associated with Crohn’s disease." (PMID 23977330, 2013). "Furthermore, GWAS run by the Wellcome Trust Case Control Consortium found a signal (rs17221417, MAF = 25.41%) in the NOD2 locus that is significantly (p = 9.4×10−12) associated with Crohn's disease." (PMID 23762022, 2013). "Interestingly, a role in autophagy is also found with immune regulators such as NOD2 and other genes associated with both Crohn's disease and mycobacterial infections." (PMID 23350010, 2013). "Mutation of NOD2/CARD15 and TLRs more often occurs in patients with Crohn's disease and confirms the hypothesis about the role of infections in affected innate immune response and intensive mucus production as features of pathogenesis of CD." (PMID 23737764, 2013). "Influence of genetic variants in the NOD2 gene may play a more important role in disease activity, behaviour and treatment of pediatric- than adult-onset Crohn’s disease (CD)." (PMID 23635032, 2013). "Moreover, mutations in NOD2 gene are associated with increased risks of Crohn’s disease (CD) development." (PMID 22815893, 2012). "Essential role for NOD2 in intestinal mucosa immunity is highlighted by the fact that mutations in the NOD2 gene are associated with increased risk to develop Crohn’s disease, an inflammatory disorder characterized by chronic inflammation of the gastrointestinal tract." (PMID 22815893, 2012). "Moreover, NOD2 deficiency or the presence of a Crohn’s disease-like Card15 mutation increased the TLR2-mediated activation of NF-κBc-Rel and Th1 responses." (PMID 23162548, 2012). "Early studies to identify possible genetic factors that were affecting the incidence of Crohn's disease, a chronic inflammatory disorder of the gastrointestinal tract that can be complicated by anaemia, stenosis, and fistulae, mapped NOD2 as a susceptibility locus." (PMID 23119165, 2012). "NOD2 mutations are linked to susceptibility to Crohn's disease." (PMID 22829933, 2012). "In addition, NOD2 polymorphisms have been associated with susceptibility to Crohn's disease, inflammatory bowel disease, pulmonary sarcoidosis and several other diseases." (PMID 22502597, 2012). "It was originally postulated that the NOD2 variants that are purported to increase the risk and severity of Crohn's disease might also contribute to the risk of GvHD, particularly gastrointestinal GvHD, due to their notable similarity in clinical symptoms." (PMID 23119165, 2012). "The NOD2 3020insC mutation blocks p38 phosphorylation of hnRNP-A1, which impairs hnRNP-A1 binding to the IL-10 locus in peripheral blood mononuclear cells from Crohn’s disease patients." (PMID 23162548, 2012). "The synthetic association paradigm is supported by the well-known association between Crohn's disease and NOD2, where three rare coding variants (G881R – MAF:0.04, R675W – MAF:0.01, and L980fs – MAF:0.02) confer high risk for Crohn's (ORs for a carrier and homozygote are 3 and 38, respectively)." (PMID 21267062, 2011).
Crohn disease (continued). "In addition, Crohn's disease NOD2 variants are associated with a deficiency of FOXP3+ Treg cells in the colonic lamina propria." (PMID 21188221, 2010). "Nod2 deficiency in mice is associated with susceptibility to Mycobacterial infection; a genus we did not consider in our study but one that has been debated as a candidate pathogen for Crohn's disease." (PMID 20531959, 2010). "Similary Annese in a large group of patients with Crohn's disease proved a relation between mutation NOD2/CARD15 and the localization in the small bowel, the narrowing form of the disease and the early age of diagnosis, but she also showed a relation between the mutation and the presence of ASCA." (PMID 20037744, 2009). "Thus, the combination of several unfavorable alleles of candidate PTPN22 in diabetes and systemic lupus erythematosus and the NOD2 gene in Crohn’s disease increases the relative risk of the disease (OR) 2-3 times." (PMID 22649616, 2009). "In addition to its role as an intracellular PRR, genetic mapping studies have identified NOD2 as a strong susceptibility gene for Crohn's disease." (PMID 18382655, 2008). "NOD2 has been identified as the first major susceptibility gene for Crohn's disease (CD)." (PMID 18096043, 2007). "A defective host defense against M. paratuberculosis in individuals bearing loss-of-function NOD2 mutations may be responsible for the invasion of the intestine and may promote chronic inflammation ultimately leading to Crohn's disease." (PMID 16322770, 2005). "Chronic inflammation, as seen in Crohn’s disease, is a known risk factor for colorectal cancer, and this inflammatory microenvironment may provide a biological basis for the observed association between NOD2 polymorphisms and increased CRC risk." (PMID 40563649, 2025). "Additionally, mutations in NF-κB–stimulating immune receptors, such as nucleotide-binding oligomerization domain-containing protein 2 (NOD2), are strongly associated with Crohn’s disease, leading to impaired microbial recognition and contributing indirectly to the chronic inflammatory cycle." (PMID 41515014, 2025). "Additionally, DCs isolated from people with Crohn’s disease carrying NOD2 variants associated with susceptibility to IBD show reduced NOD2-dependent expression of miRNA-29, which exacerbates the production of IL-12p40 after exposure to invasive adherent E. coli." (PMID 41028655, 2025). "The authors pointed out that this suppression activity could have a positive therapeutic effect in patients with Crohn’s disease who also have mutations in the gene NOD2/CARD15 complex, an intracellular receptor that activates pro-inflammatory cytokine synthesis." (PMID 36981048, 2023). "Loss of Nod2 signaling in myeloid cells contributes to tissue repair in the inflamed large intestine through lysozyme secretion by myeloid cells, which may explain the lower incidence of colitis in Crohn’s disease patients with NOD2 mutations." (PMID 37876927, 2023). "Non-coding variants affecting NOD2 may be of importance in Druze patients with Crohn's disease." (PMID 34925849, 2021). "Most importantly, however, it was demonstrated in Crohn's disease patients that genetic variants synthesize to produce Paneth cell phenotypes of Crohn's disease: i.e., the granule defects were more pronounced it the patient carried multiple NOD2 and ATG16L1 risk genes." (PMID 32351509, 2020). "Interestingly, ATG16L1 polymorphisms are also linked to Crohn's disease like NOD2." (PMID 31886308, 2019). "The mechanistic relationship between gene variants in NOD2 and Crohn’s disease pathogenesis is unclear, but could involve defective epithelial defenses, disruption of Paneth cell function, alterations in the gut microbial community, and/or defects in autophagy." (PMID 30166421, 2018).
Crohn disease (continued). "Hence we hypothesized that common NOD2 (nucleotide-binding oligomerisation domain containing 2) gene variants, known risk factors for Crohn’s disease and bacterial translocation in liver cirrhosis, increase the odds of developing SC-CIP." (PMID 28765628, 2017). "Therefore, it is tempting to speculate that NOD2 polymorphisms could increase susceptibility to Crohn’s disease by suppressing TLR homeostasis, which would trigger a pathogenic response to the commensal microbiota." (PMID 26287240, 2015). "Additionally, in contrast to the dogma, we find that the major Crohn’s disease-associated NOD2 mutations could cause a primarily immunodeficient phenotype by selectively impairing TLR4-mediated IL-12 production and host defense." (PMID 26153766, 2015). "These early GWAS showed that, with the exception of NOD2, the typical effect size of a Crohn's susceptibility locus was modest (OR < 1.3), such that the loci identified only explain a fraction of the known genetic component of Crohn's disease risk (highlighting the ‘missing heritability problem’)." (PMID 24913378, 2014). "A significant increase in the adaptive immunologic response to Crohn’s disease (CD)-associated microbial antigens, such as Pseudomonas fluorescens–related protein (I2) and Escherichia coli outer membrane porin C (anti-OmpC), is due to the presence of a defective innate immune gene (NOD2)." (PMID 25433669, 2014). "Finally, to explore if TRIM27 expression might be linked to NOD2-associated diseases in vivo, we conducted immunohistological inspection of colon sections derived from healthy and active Crohn's disease (CD) patients." (PMID 22829933, 2012). "In Crohn’s disease patients, cholecalciferol supplementation was associated with lower serum CCL20 levels, which were unaffected by NOD2 mutations." (PMID 40542081, 2025). "Mutations in nucleotide-binding oligomerization domain 2 (NOD2), also known as caspase recruitment domain-containing protein 15 (CARD15), were the first identified gene alterations conferring susceptibility to Crohn’s disease." (PMID 40649913, 2025). "Crohn disease-associated variants in ATG16L1, IRGM, and NOD2 are linked with a defect in autophagy-mediated AIEC clearance accompanied by enhanced pro-inflammatory cytokine production in epithelial cells and macrophages." (PMID 40910070, 2025). "In a cross-sectional study, serum concentrations of CCL20, 25-hydroxyvitamin D, and calcitriol were measured in 170 NOD2-genotyped Crohn’s disease patients, 80 ulcerative colitis patients, and 60 healthy controls." (PMID 40542081, 2025). "Despite extensive genome-wide association studies identifying over 200 loci associated with IBD, such as NOD2, ATG16L1, and IL-23R, these genetic variants account for only a fraction of the heritability observed in Crohn’s disease (CD) and UC." (PMID 41007813, 2025). "Since the discovery of NOD2 variation in Crohn's disease in 2001, it has been recognized that NOD2 is the most important gene in the pathogenesis of Crohn's disease." (PMID 39883213, 2024). "Among them, ATG16L1, NOD2, IRGM, and LRRK2 are autophagy-associated genes, which highlights the key role of autophagy in genetic susceptibility of Crohn's disease." (PMID 39883213, 2024). "Susceptibility loci related to intestinal macrophage functions have been unraveled in Crohn’s disease patients, including NOD2, ATG16L1, CX3CR1, IL12p40, IL23R, JAK2, STAT3, and protein tyrosine phosphatase non-receptor type 2 (PTPN2)." (PMID 39095853, 2024). "One important study showed that the rs713875 Crohn's disease risk polymorphism enhanced MTMR3 expression, which in turn increased NOD2-induced caspase-1 activation, NF-κB signaling, and cytokine secretion, and lowered PI3P thus inhibiting autophagy." (PMID 39883213, 2024).
Crohn disease (continued). "It is believed to be most relevant to Crohn’s disease based on its histological features and dependence on NOD2 (nucleotide-binding oligomerization domain 2), which has been strongly implicated in the pathogenesis of Crohn’s." (PMID 39000289, 2024). "R702W (rs2066845), G908R (rs2066845), and L1007fs (rs2066847) were discovered to be three SNPs that are specifically linked to Crohn's disease and are located in or near the LRR region of NOD2." (PMID 39883213, 2024). "The critical role of NOD2 in Crohn's disease has been confirmed by GWAS, next-generation sequencing, and functional analyses." (PMID 39883213, 2024). "Both Crohn’s disease and Blau syndrome are idiopathic, but the existence of a bacterial contributing agent is indirectly supported, given that NOD2 is a PGN sensor." (PMID 37262021, 2023). "Whole genome sequencing identified three amino acid mutations previously associated with Crohn’s disease and Parkinson’s disease as candidate variants for early onset leprosy: LRRK2 N551K, R1398H and NOD2 R702W." (PMID 36972292, 2023). "Reports have linked NOD2 to LRRK2-dependent intestinal homeostasis and RIPK2 phosphorylation, and LRRK2 polymorphisms are also associated with Crohn’s disease and leprosy susceptibility, indicating a common genetic network at play." (PMID 37262021, 2023). "Of note, polymorphisms in both NOD2 and ATG16L1 are associated with Crohn’s disease, a severe inflammatory bowel disease." (PMID 37425656, 2022). "In humans, NOD2(CARD15), a gene encoding one of cytosolic PRRs, was the first to be linked to Crohn’s disease." (PMID 36430390, 2022). "NOD2 is of particular interest in relation to inflammatory bowel diseases, especially Crohn’s disease (CD)." (PMID 35589853, 2022). "Among Caucasians, loss of function mutations in the NOD2/CARD15 gene can be identified in between 10% and 30% of patients with Crohn's disease." (PMID 36733765, 2022). "The nucleotide-binding oligomerization domain-containing protein 2/caspase recruitment domain-containing protein 15 (NOD2/CARD15) gene located on chromosome 16q12 was the first described gene connected with Crohn’s disease pathogenesis." (PMID 35634292, 2022). "The NOD2 activation is involved in autophagy induction during Crohn’s disease pathogenesis and in pneumococcal meningitis." (PMID 35954253, 2022). "Evidence indicates that NOD2 is directly involved in autophagy and inflammatory responses in Crohn’s disease, and that the increased expression of NOD2 results in NOD2-dependent impaired autophagy responses in dendritic cells." (PMID 33670592, 2021). "A fifth nonsynonymous likely pathogenic variant was found in NOD2 i.e., Asn852Ser (p.N852S), which is associated with Blau syndrome (OMIM number 186580), Crohn’s disease (OMIM number 266600), and Yao syndrome (OMIM number 617321)." (PMID 34054914, 2021). "NOD2 played important roles in the pathogenesis of some diseases, such as, oral lichen planus, Crohn’s disease, and inflammatory bowel disease." (PMID 34527446, 2021). "Consistent with our results, NOD2 expression is significantly increased in IBD, and the excessive expression of NOD2 causes impaired autophagy through activation of ATG16L1, thus resulting in cell death in Crohn’s disease." (PMID 33670592, 2021). "Accordingly, in two German cohorts patients with ileal Crohn's disease had reduced levels of HD5 and HD6, which was even more pronounced in patients carrying a mutation in the intracellular nucleotide binding oligomerization domain 2 (NOD2) receptor." (PMID 32655555, 2020). "Crohn’s disease and PD share two genetic risk factors for inflammation: LRRK2 risk alleles and a NOD2 mutation in a protein encoded by CARD15." (PMID 32575365, 2020). "Consistent with this, we found that PcLV formation was also reduced in Nod2-knockdown cells, implying a correlation between Crohn’s disease and the severity of pneumococcal infections such as pneumonia and IPD25,26." (PMID 31932716, 2020).